PTH (parathyroid hormone)
Diseases named in the same sentence as PTH in open-access papers (continued):
Sharing a sentence is not in itself a finding about the gene and the disease.
parathyroid hyperplasia (78 papers, 2011 to 2026). A hyperplasia that involves the parathyroid gland. "OCPs have been associated with parathyroid hyperplasia leading to elevated parathyroid hormone (PTH) and calcium levels; however, the calcium levels were in the normal reference range in these patients, thus obviating the need to measure PTH." (PMID 37239122, 2023). "The blood PTH levels are increased 5–10 fold, with evident PTH-associated complications such as fractures and parathyroid hyperplasia." (PMID 35095753, 2021). "In animals with normal renal function, the elevation in FGF23 causes a reduction in PTH production, but as parathyroid hyperplasia develops, there is a lower expression of parathyroid FGFR and Klotho receptors, which prevent any inhibitory effect of FGF2310." (PMID 32913635, 2020). "Additionally, parathyroid hyperplasia can happen during pregnancy, elevating parathyroid hormone levels and raising the risk of osteonecrosis." (PMID 40416257, 2025). "These PTH dynamics suggest that the more vigorous response of older postmenopausal women might be attributable to decreased suppression of baseline PTH secretion, which could also possibly be caused by mild parathyroid gland hyperplasia." (PMID 32803112, 2020). "In this case report, we present a rare case of PHPT due to single‐gland parathyroid hyperplasia and an ectopic paraesophageal adenoma, managed successfully with bilateral neck exploration and intraoperative PTH monitoring." (PMID 41502796, 2026). "Current treatment based on activating the parathyroid calcium-sensing receptor (CaSR) using calcimimetics such as Cinacalcet, aims to decrease plasma PTH levels and inhibit the progression of parathyroid hyperplasia." (PMID 39761264, 2025). "A decrease in serum calcium levels stimulates the secretion and synthesis of PTH as well as parathyroid gland hyperplasia." (PMID 39388484, 2024). "Destruction of the parathyroid gland hyperplasia using RFA is the main reason for the decrease in PTH." (PMID 39697216, 2024). "The crucial result of that action is a decrease in the secretion of parathyroid hormone (PTH) in a dose-dependent manner, which suppresses parathyroid hyperplasia." (PMID 36672533, 2022). "The normalization of parathyroid function is related to the inhibition of parathyroid hyperplasia and the reduction of parathyroid hormone synthesis and secretion." (PMID 36267284, 2022). "This causes progressive parathyroid gland hyperplasia with associated reduced responsiveness to calcium, vitamin D and FGF23 levels that gradually leads to autonomous parathyroid hormone secretion, (tertiary hyperparathyroidism)." (PMID 34626363, 2022). "SHPT is a common complication of CKD and is followed by disorders of calcium and phosphorus metabolism, abnormal PTH secretion, and parathyroid hyperplasia." (PMID 32746794, 2020). "In summary, the present study suggests that evocalcet can improve ectopic calcification and parathyroid hyperplasia by inhibiting PTH secretion in SHPT patients similarly to cinacalcet." (PMID 32343734, 2020). "Patients with APA had a significantly higher median serum Ca level compared with those with parathyroid hyperplasia (P = 0.019) and a significantly higher median PTH level compared with those with PA (P < 0.001)." (PMID 31751311, 2019). "Median serum Ca was significantly higher in atypical parathyroid adenoma patients than parathyroid hyperplasia patients (P = 0.019) and median PTH was significantly higher in APA compared to PA patients (P < 0.001)." (PMID 31751311, 2019). "It is followed by disorders of calcium and phosphorus metabolism, parathyroid hyperplasia, and abnormal PTH secretion." (PMID 31537128, 2019). "The ‘content’ of the different noduli in severe parathyroid hyperplasia is determining the PTH secretion." (PMID 26058796, 2015). "There are a number of endpoints that can be examined in preclinical models of SHPT such as effects on PTH, serum phosphorus and calcium levels and parathyroid gland hyperplasia." (PMID 24884838, 2014).
parathyroid hyperplasia (continued). "Preoperatively, 24 months after high-dose cinacalcet hydrochloride, we observed a persistently elevated intact parathyroid hormone serum level, and detected clear parathyroid gland hyperplasia regression on ultrasound." (PMID 23232027, 2012). "Primary hyperparathyroidism, more common and appears to be characterised by autonomous overproduction (adenoma or hyperplasia of the parathyroid gland) of PTH, leading to high plasma calcium and low plasma phosphate, and increased bone resorption with possible increase in urinary calcium excretion." (PMID 41295288, 2025). "In the current study, we used US-guided RFA to treat parathyroid hyperplasia in 103 patients with SHPT caused by CKD and showed that serum calcium, phosphorus, and PTH levels decreased significantly after RFA in patients with SHPT, which was consistent with the results of our previous study." (PMID 37345712, 2023). "Therefore, up-regulation or activation of Klotho can be used as a therapeutic approach to regulate circulating PTH levels and parathyroid hyperplasia." (PMID 36267284, 2022). "Since GFR reduction is a direct cause of PTH elevation, it is difficult to determine whether high PTH after KTx is mainly due to low GFR or to parathyroid gland hyperplasia." (PMID 35710357, 2022). "Taken together, these results may help unravel novel mechanisms underlying the development of SHPT as well as design strategies to prevent parathyroid hyperplasia and manage PTH secretion." (PMID 32913635, 2020). "In our study, although not statistically significant, patients with APA had lower vitamin D levels than those with PA and parathyroid hyperplasia, which may have contributed to the higher PTH levels found among patients with APA." (PMID 31751311, 2019). "Long-term disorders of calcium and phosphate may lead to parathyroid hyperplasia, which will secrete more parathyroid hormone to balance the electrolyte concentrations." (PMID 28482911, 2017). "The pregnancy-related maternal parathyroid gland hyperplasia with high levels of parathyroid hormone may also contribute." (PMID 27795792, 2016). "However, a review of her chronic trends in PTH clearly showed that the calcium rise was acute and that the PTH of 84 ng/L was relatively “suppressed” in the context of pre-existing advanced parathyroid hyperplasia." (PMID 27683096, 2016). "It is characterized by the excessive release of parathyroid hormone (PTH) from the parathyroid glands in response to a combination of elevated phosphorus (P), decreased calcium (Ca), and decreased 1,25-dihydroxyvitamin D levels, resulting in parathyroid hyperplasia." (PMID 32816132, 2021). "It results from impaired regulation of calcium, phosphorus, and vitamin D metabolism, leading to excessive secretion of parathyroid hormone (PTH) and progressive parathyroid gland hyperplasia." (PMID 41492600, 2025). "sHPT in CKD occurs with a combination of functional and structural changes in the parathyroid glands resulting in increased parathyroid hormone (PTH) biosynthesis and secretion as well as in parathyroid hyperplasia." (PMID 39761264, 2025). "SHPT is characterized by an elevation of serum parathyroid hormone (PTH) and parathyroid gland hyperplasia." (PMID 35681076, 2022). "Parathyroid hyperplasia is also a characteristic feature of SHPT and its progression leads to hypersecretion of PTH from the parathyroid glands and this in turn leads to altered mineral metabolism." (PMID 32343734, 2020). "Persistently elevated levels of parathyroid hormone (PTH) and parathyroid hyperplasia are features of sHPT." (PMID 28853301, 2017). "Some studies suggest that diabetic patients may have a blunted PTH response in early CKD stages, while others report a higher prevalence of parathyroid hyperplasia in diabetic ESRD populations." (PMID 41301699, 2025).
parathyroid hyperplasia (continued). "In our cohort, we had only one patient with a multi-gland disease, and in the five cases where parathyroid hyperplasia was found, we did not observe any difference in the PTH dynamics perioperatively." (PMID 35407623, 2022). "By reducing parathyroid hyperplasia, evocalcet might suppress the development of SHPT, thereby inhibiting the increase of serum PTH and thus prevent ectopic calcification at an initial stage." (PMID 32343734, 2020). "Tertiary hyperparathyroidism is characterized by severe parathyroid hyperplasia with autonomous secretion of PTH that is no longer adequately responsive to the plasma calcium concentration." (PMID 27579039, 2016). "A recent study demonstrated that the ET-1 receptor blocker, Bosentan, failed to reduce parathyroid hyperplasia and PTH values in 5/6 of nephrectomized rats." (PMID 25068056, 2014). "In the experience of Mischis-Troussard, the frequency of parathyroid hyperplasia was high (20%), but not enough to conclude that the proportion of hyperplasia is higher in PHP with normal serum PTH levels." (PMID 31074404, 2019). "However, with the development of parathyroid hyperplasia, Klotho expression is reduced and the high FGF23 is not able to inhibit PTH production and parathyroid cell proliferation." (PMID 32913635, 2020).
osteomalacia (74 papers, 2007 to 2026). Disorder caused by an interruption of the mineralization of organic bone matrix leading to bone softening, bone pain, and weakness. "The diagnostic criteria for biochemical osteomalacia were serum levels of a 25-hydroxy vitamin D3 (25(OH)D) concentration < 30 nmol/L, a parathyroid hormone (PTH) concentration > 6.9 pmol/L and an alkaline phosphatase (ALP) concentration > 1.8 ukat/L." (PMID 41735914, 2026). "Elevated ALP levels appear to be caused by osteomalacia and/or osteodystrophy due to vitamin D3 deficiency in Najdi lambs, as it is associated with elevated circulatory levels of PTH, resulting in lower circulatory phosphorus levels." (PMID 40231299, 2025). "In contrast, low-turnover bone disease comprises adynamic bone disease and osteomalacia, which are associated with low PTH levels or PTH resistance." (PMID 34207816, 2021). "The level of 25-hydroxy-vitamin D (25-OH D) was 7.5 ng/mL (<20 ng/mL is defined as deficiency), and parathyroid hormone (PTH) was 560 pg/mL (reference range: 160–520 pg/mL), indicating osteomalacia." (PMID 31295706, 2019). "Parathyroid hormone was higher in the leaflet group, fitting with the lower vitamin D and the greater risk of osteomalacia in this group." (PMID 27785646, 2017). "A secondary aim was to explore the association between knowledge about osteomalacia and vitamin D and parathyroid hormone (PTH) levels." (PMID 27785646, 2017). "Collectively, these factors, with the elevated PTH serum levels under a vitamin D and calcium deficient diet indicate osteomalacia." (PMID 23977109, 2013). "Besides that, increased PTH is associated with a higher risk of fractures, bone loss, and osteomalacia." (PMID 35514345, 2022). "When serum PTH level is <150 pg/mL, the fracture is most likely due to adynamic bone disease or osteomalacia." (PMID 40008355, 2025). "The clinical outcome of persistently elevated PTH is any of the following: osteitis fibrosa cystica, osteomalacia and adynamic bone disease." (PMID 38785509, 2024). "Osteomalacia is possibly the least severe of the three, arising from adequate use of medication aiming at reducing PTH levels." (PMID 38785509, 2024). "According to this approach 5% of our cohort with elevated PTH required treatment for biochemical signs of osteomalacia." (PMID 38750418, 2024). "Indeed, Pi repletion further increased FGF23 and PTH levels, which exacerbated urinary Pi excretion, osteomalacia, and cortical bone expansion, similarly to studies performed in humans." (PMID 37943605, 2023). "Thus, PTH is associated with the onset and progression of low BMD due to accelerated bone resorption and osteomalacia." (PMID 32617522, 2020). "Interestingly, this result differs from our previous report in which we describe that the osteomalacia and the high Opn levels in Fgf23−/−/PTH−/− mice persisted." (PMID 22615584, 2012). "After excluding renal impairment and liver disease, we defined biochemical osteomalacia as ALP >130 IU/L and aCa <2.0 mmol/L and elevated PTH >9.2 or >6.8 pmol/L, depending on the assay." (PMID 39862119, 2025). "Only following prolonged deprivation of calcium and vitamin D do typical biochemical markers of osteomalacia, such as ALP and PTH, start to rise in the bloodstream." (PMID 36558513, 2022). "By contrast, phosphate was decreased in several affected family members while PTH and FGF23 remained in normal range and bone biopsies excluded osteomalacia." (PMID 34258505, 2021). "Case 4 showed no muscle or osteomalacia-associated symptoms and had normal ALP and PTH levels; however, the preoperative serum phosphate level was absent." (PMID 37033241, 2023). "The values of O.Th in our specimens were all within normal range, unlike osteomalacia, it would be useful to know 25(OH)D and PTH levels in order to exclude the possibility of mild insufficiency and secondary hyperparathyroid effects." (PMID 29615973, 2018).
osteomalacia (continued). "Additional limitations include that adolescents were not screened for osteomalacia; serum parathyroid hormone values were not routinely checked in those who were D-deficient; however, several performed clinically were within normal ranges." (PMID 22571731, 2012). "An alternate set of criteria for the diagnosis of osteomalacia for patients without liver or kidney disease is the presence of elevated parathyroid hormone, elevated total alkaline phosphatase, low urinary calcium, and either low calcidiol levels (<30 nmol/L) or low calcium intake (<300 mg per day)." (PMID 40725553, 2025). "The lack of PTH testing may have been because osteomalacia was not under consideration, although lack of knowledge to test and limited availability for primary care may also have contributed." (PMID 39862119, 2025). "Moreover, increased serum PTH levels with low BALP may reflect different degrees of the multifactorial skeletal resistance to PTH, just as the presence of aluminum overload, osteomalacia, Paget’s disease, or lytic bone lesions should be excluded." (PMID 35631265, 2022). "Such a reduction in Opn levels could not be observed in Fgf23−/−/PTH−/− mice, and these mice showed sustained osteomalacia." (PMID 22615584, 2012).
metabolic syndrome (69 papers, 2009 to 2025). A cluster of metabolic risk factors for CARDIOVASCULAR DISEASES and TYPE 2 DIABETES MELLITUS. "Of interest, PTH concentrations were associated with metabolic syndrome and lipid levels in numerous studies, particularly with TG and HDL-C levels, even independently of the BMI, with possibly sexually dimorphic associations." (PMID 38412162, 2024). "Similar observations were described in a study that investigated 25(OH)D levels in patients with metabolic syndrome—low circulating 25(OH)D was associated with high PTH levels." (PMID 36771474, 2023). "In multivariate logistic regression analysis, gender specific association patterns of PTH and vitamin D with metabolic syndrome were observed." (PMID 29348466, 2018). "Some studies have reported associations between PTH and metabolic syndrome components, but in the NHANES 2001–2006 cohort, diastolic blood pressure is the only cardiovascular risk factor independently associated with greater PTH." (PMID 24505486, 2014). "In another study in obese subjects, PTH was paradigmatically associated to the metabolic syndrome via other biomarkers like vitamin D and magnesium, albeit this association was only significant in women." (PMID 24618074, 2014). "Risk of metabolic syndrome due to PTH and the effects of adjusting for individual components of the metabolic syndrome on PTH odds ratios in a logistic regression analysis." (PMID 23596520, 2013). "Multivariate logistic regression analysis for determining the effect of ethnicity, PTH and 25(OH)D on risk of metabolic syndrome." (PMID 23596520, 2013). "Apart from this, high PTH levels are deleterious for bone health and are also associated with calcific aortic stenosis, the metabolic syndrome, and cancer risk." (PMID 22518130, 2012). "Further, low serum levels of 25-hydroxyvitamin D (25 [OH]D) and magnesium have been associated with increased risk of the metabolic syndrome (MS), and recently, a possible link between PTH and MS has been reported." (PMID 19187564, 2009). "This study aimed to determine the free and bioavailable 25(OH)D characteristics, estimate their thresholds based on parathyroid hormone (PTH) and bone turnover markers (BTMs), assess their associations with the risk of metabolic syndrome (MetS), and evaluate their potential advantages." (PMID 37736136, 2023). "Increased/decreased PTH secretion can be a possible explanation for commonly observed negative relationships of serum VitD with centripetal obesity and metabolic syndrome and the in this study found positive association with peripheral fat accumulation (hip circumference and leg FM%)." (PMID 34490320, 2021). "Although several lines of evidence indicate that serum PTH may be associated with metabolic disturbances, to our knowledge, only few studies have addressed the combined effect of serum PTH and vitamin D on metabolic syndrome and visceral adiposities." (PMID 22111014, 2011). "Furthermore, it has been recently stated that elevated PTH levels may increase the risk of cardiovascular diseases and may also be linked to metabolic syndrome." (PMID 36615081, 2022). "Additionally maintaining lower PTH may also contribute to weight loss and prevent metabolic syndrome." (PMID 31126121, 2019). "Indeed, reduction of PTH levels after successful parathyroidectomy is associated to decrease of blood pressure, fasting blood glucose, serum triglycerides, and cholesterol, with reduction of the percentage of the metabolic syndrome (38% versus 28%, resp)." (PMID 22719761, 2012). "Patients with MCP-1 concentrations ≥ 540 pg/mL had higher BMI, more history of dyslipidemia, higher PTH, and lower serum ferritin." (PMID 41003499, 2025). "In Model 2, T-score was set as the dependent variable and adjustments were made for MCV, age, serum phosphate level, BMI, parathyroid hormone level, dyslipidemia, and gastrointestinal tract ulcer history." (PMID 35454336, 2022).